PELO (pelota mRNA surveillance and ribosome rescue factor)
Description:
Component of the Pelota-HBS1L complex, a complex that recognizes stalled ribosomes and triggers the No-Go Decay (NGD) pathway. In the Pelota-HBS1L complex, PELO recognizes ribosomes stalled at the 3' end of an mRNA and engages stalled ribosomes by destabilizing mRNA in the mRNA channel. Following mRNA extraction from stalled ribosomes by the SKI complex, the Pelota-HBS1L complex promotes recruitment of ABCE1, which drives the disassembly of stalled ribosomes, followed by degradation of damaged mRNAs as part of the NGD pathway. As part of the PINK1-regulated signaling, upon mitochondrial damage is recruited to the ribosome/mRNA-ribonucleoprotein complex associated to mitochondrial outer membrane thereby enabling the recruitment of autophagy receptors and induction of mitophagy.
Synonyms: CGI-17; PRO1770
Tractability: Small molecule: a structure with a bound ligand is known. PROTAC: UniProt records ubiquitination sites on it; ubiquitination databases record sites on it; its protein half-life has been measured.
Gene: Protein-coding gene on chromosome 5 (52,787,916 to 52,804,044, forward strand). Ensembl gene ENSG00000152684.
Subcellular location: Cytoplasm
Subcellular location (Human Protein Atlas): Nucleoli fibrillar center; Mitotic chromosome; Nucleoplasm
Pathways (Reactome):
Metabolism of proteins: PELO:HBS1L and ABCE1 dissociate a ribosome on a non-stop mRNA
Gene Ontology:
Molecular function: protein binding; ribosome binding; stalled ribosome sensor activity
Biological process: nuclear-transcribed mRNA catabolic process, no-go decay; rescue of stalled ribosome; ribosome disassembly; nuclear-transcribed mRNA catabolic process, non-stop decay; RNA surveillance
Cellular component: cytosolic ribosome; Dom34-Hbs1 complex; cytosol; cytoplasm
Genetic constraint (gnomAD): Loss-of-function variants: 19 observed, 27.66 expected, observed/expected ratio (o/e) 0.69, 90% interval 0.48 to 1.01. The upper end of that interval is the gene's LOEUF score, 1.01, which puts it in group 4 of 6, group 1 being the genes least tolerant of losing a copy. Missense variants: 498 observed, 524.76 expected, observed/expected ratio (o/e) 0.95, 90% interval 0.88 to 1.02. Synonymous variants: 196 observed, 206.81 expected, observed/expected ratio (o/e) 0.95, 90% interval 0.84 to 1.07.
Homologues: Orthologues: chimpanzee PELO (99% identical), macaque PELO (99% identical), guinea pig PELO (98% identical), rabbit PELO (98% identical), pig PELO (98% identical), rat Pelo (97% identical), mouse Pelo (97% identical), zebrafish pelo (82% identical), tropical clawed frog pelo (81% identical), Drosophila melanogaster pelo (66% identical), Caenorhabditis elegans pelo-1 (58% identical).
Diseases named in the same sentence as PELO in open-access papers:
PELO is named in the same sentence as 14 diseases in open-access papers, as found by Europe PMC text mining. Sharing a sentence is not in itself a finding about the gene and the disease. The quoted sentences say what the papers report.
breast carcinoma (1 paper, 2023). "This study developed a signature featuring 8 OARGs (HLA-B, RBBP8, SPRY4, WT1, WWOX, UPRT, PELO, ZNF208) and determined its prognostic and functional implications in breast cancer patients." (PMID 36960071, 2023).
developmental delays (1 paper, 2025). "For instance, Hbs1L deficiency, which affects Pelo levels and ribosome recycling, is associated with congenital anomalies and developmental delays, though this is linked to HBS1L mutations rather than PELO itself." (PMID 40785597, 2025).
diabetes (1 paper, 2021). "The rs77704739 variant was significantly associated with gene expression of PELO in multiple tissues, including diabetes-relevant tissues such as adipose tissue, skeletal muscle, and pancreas." (PMID 33893285, 2021).
hepatoma (1 paper, 2010). "To investigate whether the overexpression of PELO alters the anchorage-independent growth ability of HepG2 hepatoma cells, we compared the ability of L3 and L6 to growth in soft agar." (PMID 20406461, 2010).
prostate carcinoma (1 paper, 2025). A carcinoma that arises from epithelial cells of the prostate gland. "Additionally, PELO promotes prostate cancer progression by enhancing PLK1-induced ubiquitination and degradation of Smad4." (PMID 40764425, 2025).
type 2 diabetes (1 paper, 2021). "A second recessive variant with large effect, rs77704739, near the PELO gene, is associated with a fourfold risk for type 2 diabetes (MAF = 0.036, OR [CI 95%] = 4.3 [2.7–6.9], p = 1.75 × 10−8)." (PMID 33893285, 2021).
cancer (2 papers, 2025). A tumor composed of atypical neoplastic, often pleomorphic cells that invade other tissues. "Together, our findings indicate PELO as a promising therapeutic target for a large patient population with cancers characterized as MSI-H with deleterious TTC37 mutations or with biallelic 9p21.3 deletions involving FOCAD." (PMID 39910293, 2025). "To assess how SKIc-deficient cancer cells responded to PELO suppression, we performed gene expression profiling." (PMID 39910293, 2025). "In MSI-H cancers, PELO is required owing to MSI-H-associated mutations in TTC37 (also known as SKIC3), a critical component of the SKIc." (PMID 39910293, 2025). "We found that the cancer patient treatment-relevant relation between PELO and FOCAD, or the experimentally identified interactions between SLC7A2 and SLC7A1, or SLC7A6 and SLC7A1 were best predicted upon combinatorial normalization (Dataset EV1)." (PMID 40263591, 2025). "Analysis of large-scale CRISPR screening data, combined with experiments in patient-derived tumour organoid models, identifies PELO as a potential therapeutic target in chromosomal 9p21.3-deleted cancers and microsatellite-unstable cancers harbouring specific mutations." (PMID 39910293, 2025).
tumor (2 papers, 2023). "PELO negatively regulates cell migration and metastasis in vivo.The results implied that BF-TK/GCV inhibited tumor metastasis through these proteins." (PMID 37511481, 2023). "PELO is a new HER-signaling regulator and was suggested to play a role in inhibiting tumor cell proliferation and metastasis." (PMID 36960071, 2023).
infection (1 paper, 2024). The state of being infected such as from the introduction of a foreign agent such as serum, vaccine, antigenic substance or organism. "After WSL infection with ASFV, we found a significant decrease in PELO expression in the cells, suggesting that p72 may regulate the translation process of the ASFV genome by regulating PELO expression." (PMID 38481793, 2024).
PELO also shares sentences with these, for which no sentence is quoted: cardiovascular disease (1 paper); Esotropia (1); keloid (1); macular degeneration (1); viral infection (1).